PWRN1 (Prader-Willi region non-protein coding RNA 1)
Synonyms: NCRNA00198; LOHAN1; PWRN3
Gene: Long non-coding RNA gene on chromosome 15 (24,101,827 to 24,823,365, forward strand). Ensembl gene ENSG00000259905.
Diseases named in the same sentence as PWRN1 in open-access papers:
PWRN1 is named in the same sentence as 10 diseases in open-access papers, as found by Europe PMC text mining. Sharing a sentence is not in itself a finding about the gene and the disease. The quoted sentences say what the papers report.
gastric cancer (4 papers, 2020 to 2025). A primary or metastatic malignant neoplasm involving the stomach. "Prader-Willi region non-protein coding RNA 1(PWRN1) located in chromosome 15 and up-regulated PWRN1 suppressed cell proliferation and tumor growth in gastric cancer." (PMID 33083119, 2020). "Overexpressed PWRN1 could inhibit the proliferation and metastasis of gastric cancer cells and tumor growth." (PMID 34295352, 2021). "PWRN1 was significantly underexpressed in gastric cancer tissues and cells." (PMID 34295352, 2021). "Furthermore, PWRN1 may regulate miR-425-5p expression by acting as its sponge in gastric cancer cells." (PMID 34295352, 2021).
hepatocellular carcinoma (2 papers, 2023 to 2025). A malignant tumor that arises from hepatocytes. "Conversely, lncRNA PWRN1 inhibits hepatocellular carcinoma (HCC) growth, invasion, and metastasis by forming a stable tetramer and increasing PKM2 activity, suppressing aerobic glycolysis and reducing lactate levels." (PMID 40223929, 2025).
breast carcinoma (1 paper, 2023). "It is worth mentioning that the four verified lncRNAs as a miRNA sponge are widely reported in cancers, such as the GATA3-AS1/miR-495-3p/CENPU axis in breast cancer, and the PWRN1/miR-214-5p axis in osteosarcoma." (PMID 36874970, 2023).
head and neck cancer (1 paper, 2023). A primary or metastatic malignant neoplasm affecting the head and neck. "It was interesting to note that, amongst the six that did not display a significant effect was a lncRNA, AC087463.1, herein named LOHAN1 (LncRNA Oncogene in Head and Neck cancer—ENST00000568541 at the PWRN1 locus), which appeared as a potential driver in the Head and Neck (HN) tumour cohort." (PMID 37291246, 2023).
cancer (5 papers, 2020 to 2023). A tumor composed of atypical neoplastic, often pleomorphic cells that invade other tissues. "One of the major findings in this study was that cancer patients with low PWRN1 expression had much worse OS than those with high PWRN1." (PMID 37371065, 2023). "PWRN1 overexpression suppress xenograft growth in vivo and cancer cell migration in vitro (Jiang, Wang & Lu, 2020)." (PMID 36874970, 2023). "The DElncRNA or DEGs in PWRN1-mediated ceRNA network was related to clinical outcomes or cancer development somehow." (PMID 33083119, 2020). "Additionally, when PWRN1 lncRNA was overexpressed in OS cell lines, the amount of cancer cell proliferation was drastically suppressed, and chemoresistance to cisplatin was markedly reduced." (PMID 37371065, 2023). "Notably, miR-214-5p (a human microRNA) was identified as a possible ceRNA candidate for PWRN1, and the overexpression of miR-214-5p reversed the anti-cancer effects of PWRN1 on OS cell proliferation and chemoresistance." (PMID 37371065, 2023).
tumor (3 papers, 2020 to 2023). "LOHAN1 is transcribed from the same locus as the lncRNA PWRN1, previously reported as a tumour suppressor in gastric cancer." (PMID 37291246, 2023). "But in our study, high expression PWRN1 was related to worse clinical outcomes, which might be because PWRN1 was a strongly tissue-specific lncRNA so that PWRN1 could both act as proliferation-promoting and tumor suppressor role." (PMID 33083119, 2020).
PWRN1 also shares sentences with these, for which no sentence is quoted: Intellectual disability (1 paper); Obesity (1); osteosarcoma (1); psychosis (1).